ENSG00000251569 (novel protein)
Gene: Protein-coding gene on chromosome 2 (169,479,480 to 169,525,922, forward strand). Ensembl gene ENSG00000251569.
Genetic constraint (gnomAD): Loss-of-function variants: 26 observed, 40.91 expected, observed/expected ratio (o/e) 0.64, 90% interval 0.47 to 0.88. Missense variants: 382 observed, 439.09 expected, observed/expected ratio (o/e) 0.87, 90% interval 0.8 to 0.95. Synonymous variants: 120 observed, 149.55 expected, observed/expected ratio (o/e) 0.8, 90% interval 0.69 to 0.93.